Y_RNA (Y RNA )
Gene: Miscellaneous RNA gene on chromosome X (18,395,994 to 18,396,095, reverse strand). Ensembl gene ENSG00000207025.
Homologues: Orthologues: chimpanzee Y_RNA (100% identical), macaque Y_RNA (94% identical). Paralogues in human: Y_RNA (89% identical), Y_RNA (88% identical), Y_RNA (86% identical), RNY3 (85% identical), Y_RNA (85% identical), RNY3P1 (84% identical), Y_RNA (84% identical), Y_RNA (83% identical), RNY3P14 (82% identical), RNY3P16 (82% identical), Y_RNA (82% identical), Y_RNA (81% identical), and 96 more.